ENSG00000258653 (novel protein)
Gene: Protein-coding gene on chromosome 14 (73,851,971 to 73,932,278, forward strand). Ensembl gene ENSG00000258653.
Genetic constraint (gnomAD): Missense variants: 171 observed, 190.8 expected, observed/expected ratio (o/e) 0.9, 90% interval 0.79 to 1.02. Synonymous variants: 53 observed, 66.04 expected, observed/expected ratio (o/e) 0.8, 90% interval 0.64 to 1.01.